TMEM98 (transmembrane protein 98)
Description:
Functions as a negative regulator of MYRF in oligodendrocyte differentiation and myelination. Interacts with the C-terminal of MYRF inhibiting MYRF self-cleavage and N-fragment nuclear translocation. The secreted form promotes differentiation of T helper 1 cells (Th1).
Synonyms: DKFZP564K1964; TADA1
Tractability: Antibody: UniProt places it where antibodies can reach, with high confidence; its Gene Ontology location is reachable by antibodies, with high confidence; UniProt predicts a signal peptide or a membrane-spanning region. PROTAC: ubiquitination databases record sites on it.
Gene: Protein-coding gene on chromosome 17 (32,927,910 to 32,945,106, forward strand). Ensembl gene ENSG00000006042.
Subcellular location: Cell membrane; Secreted; Secreted, extracellular exosome; Endoplasmic reticulum membrane
Subcellular location (Human Protein Atlas): Nucleoplasm
Gene Ontology:
Molecular function: protein binding
Biological process: negative regulation of myelination; negative regulation of oligodendrocyte differentiation; T-helper 1 cell differentiation; negative regulation of protein localization to nucleus; negative regulation of protein processing
Cellular component: endoplasmic reticulum; extracellular exosome; extracellular region; nucleoplasm; plasma membrane; endoplasmic reticulum membrane; membrane
Genetic constraint (gnomAD): Loss-of-function variants: 18 observed, 24.89 expected, observed/expected ratio (o/e) 0.72, 90% interval 0.5 to 1.07. The upper end of that interval is the gene's LOEUF score, 1.07, which puts it in group 4 of 6, group 1 being the genes least tolerant of losing a copy. Missense variants: 241 observed, 296.46 expected, observed/expected ratio (o/e) 0.81, 90% interval 0.73 to 0.9. Synonymous variants: 103 observed, 113.29 expected, observed/expected ratio (o/e) 0.91, 90% interval 0.77 to 1.07.
Gene-disease validity (ClinGen):
ClinGen rates the evidence that TMEM98 causes each of these diseases.
nanophthalmos 4 (autosomal dominant): Limited.
Homologues: Orthologues: chimpanzee TMEM98 (100% identical), macaque TMEM98 (100% identical), mouse Tmem98 (99% identical), rat Tmem98 (99% identical), pig TMEM98 (98% identical), rabbit TMEM98 (98% identical), guinea pig TMEM98 (98% identical), dog TMEM98 (97% identical), tropical clawed frog tmem98 (86% identical), zebrafish tmem98 (81% identical), Caenorhabditis elegans K10C3.4 (30% identical).
Diseases named in the same sentence as TMEM98 in open-access papers:
TMEM98 is named in the same sentence as 19 diseases in open-access papers, as found by Europe PMC text mining. Sharing a sentence is not in itself a finding about the gene and the disease. The quoted sentences say what the papers report.
nanophthalmos (8 papers, 2018 to 2023). "To further investigate the role of TMEM98 in ocular development we used CRISPR/Cas9 editing to create a mouse model of human TMEM98-associated nanophthalmos." (PMID 37419942, 2023). "In humans, the p.(Ala193Pro) variant can clearly act in a dominant manner, and indeed all TMEM98-associated nanophthalmos pedigrees reported thus far show autosomal dominant inheritance." (PMID 37419942, 2023). "Intriguingly, nanophthalmos is the phenotypic opposite of high myopia, a paradox that is underscored by a report of 3 variants in TMEM98 associated with high myopia in Chinese patients." (PMID 32667907, 2020). "MYRF itself has since been linked to nanophthalmos in humans and retinal degeneration in mice, similar to TMEM98." (PMID 31961879, 2020). "Nanophthalmos is associated with a thickened sclera, and it is possible that the cause of TMEM98 associated nanophthalmos involves misregulation of the same pathway which leads to weaker sclera in this loss-of-function model." (PMID 32236127, 2020). "Loss-of-function of Tmem98 in the RPE results in eye enlargement whereas missense mutations that cause dominant nanophthalmos in humans result in retinal defects when homozygous in the mouse but no significant change in eye size." (PMID 32236127, 2020). "Mutations in human TMEM98 are found in patients with nanophthalmos (very small eyes) and variants near the gene are associated in population studies with myopia and increased eye size." (PMID 32236127, 2020). "Unexpectedly, given the association between Tmem98 and nanophthalmos, adult eyes in which Tmem98 had been knocked-out by Tyr-Cre were greatly enlarged and fundal imaging revealed that there was extensive retinal degeneration in the mutant eyes." (PMID 32236127, 2020). "In humans, mutations of TMEM98 appear to cause dominant nanophthalmos, whilst in population studies variants 5’ of this gene are associated with myopia." (PMID 32236127, 2020). "Fifth, MYRF interacts with TMEM98, a gene recently implicated in nanophthalmos in 3 families, at both regulatory and direct protein-protein levels." (PMID 31048900, 2019). "We showed that MYRF interacts with and regulates expression of another membrane protein, TMEM98, which has been implicated in nanophthalmos." (PMID 31048900, 2019). "We have further uncovered a role for MYRF in the early development of the RPE, and a regulatory and physical interaction with TMEM98 another RPE expressed gene implicated in nanophthalmos." (PMID 31048900, 2019). "This direct comparison of a TMEM98 variant in mouse and human suggests that certain nanophthalmos-associated phenotypes are not only a consequence of a smaller eye, but that TMEM98 may itself play a primary role in retinal and scleral structure and integrity." (PMID 37419942, 2023). "Besides Prss56, Tmem98 was the only other differentially expressed gene that has previously been implicated in nanophthalmos and was found to be significantly downregulated in the retina from Prss56-/- mice compared to control Prss56+/- mice." (PMID 33755662, 2021). "However, clinical correlation, in silico and co-segregation evidence is strongly suggestive of TMEM98 variant as the plausible cause of nanophthalmos in this family." (PMID 33203948, 2020). "Mutations in TMEM98 have been found in nanophthalmos patients." (PMID 32236127, 2020). "Interestingly, heterozygous mutations of MYRF in humans lead to nanophthalmos, suggesting loss of this protein has the opposite effect to the activation we suggest occurs in the Tmem98 deletion eyes." (PMID 32236127, 2020). "However, two missense mutations in TMEM98, A193P and H196P, and a small deletion that removes the distal part of exon 4 and the beginning of the adjacent intron are associated with dominant nanophthalmos in humans." (PMID 32236127, 2020). "We defined a novel TMEM98 variant p.(Arg203Pro), which segregates with nanophthalmos in one family." (PMID 33203948, 2020).
nanophthalmos (continued). "Similarly, nanophthalmos-associated human variants in TMEM98 when knocked-in to the Tmem98 locus in mice cause retinal white spots and retinal folds, but no appreciable difference in ocular size." (PMID 31048900, 2019). "Additionally, we show that Myrf is expressed in ocular tissues and plays an important role in the development of the retina and RPE, and that it genetically and physically interacts with Tmem98, another gene implicated in nanophthalmos." (PMID 31048900, 2019). "When pathogenic mutations in other genes causing nanophthalmos in humans have been studied in mice it has also been found that significant changes in eye size do not result, rather the predominant phenotype is retinal defects in line with what we found with Tmem98." (PMID 32236127, 2020). "To date, six genes (PRSS56, MFRP, TMEM98, CRB1, BEST1, and MYRF) have been implicated in familial forms of nanophthalmos, with PRSS56 and MFRP mutations being the most prevalent among multiple cohorts." (PMID 33755662, 2021). "A molecular and cellular explanation for the involvement of TMEM98 in eye development and the onset of nanophthalmos is still missing." (PMID 31961879, 2020). "We have defined the diagnostic yield of sequencing the coding variants in PRSS56, MFRP, TMEM98, MYRF, CRB1, and BEST1 in a large cohort of patients with nanophthalmos and high hyperopia." (PMID 33203948, 2020). "We went on to identify protein partners of TMEM98 and found that it interacts with a protein called MYRF, mutations in which also cause nanophthalmos." (PMID 32236127, 2020). "To date, five genes (i.e., MFRP, TMEM98, PRSS56, BEST1, and CRB1) and two loci have been implicated in familial forms of nanophthalmos." (PMID 29862063, 2018). "This study was built upon their previous investigation, which found that when two known missense mutations of TMEM98 in human autosomal dominant nanophthalmos were engineered into mice, they did not have nanophthalmos, but instead developed retinal pathology." (PMID 32667907, 2020). "While six genes have been implicated in this hereditary condition (MFRP, PRSS56, MYRF, TMEM98, CRB1,VMD2/BEST1), the relative contribution of these to nanophthalmos or to less severe high hyperopia (≥ + 5.50 spherical equivalent) has not been fully elucidated." (PMID 33203948, 2020). "In our human TMEM98A193P/+ nanophthalmos case, the maximum recorded intraocular pressure (IOP) (RE: 33 mmHg, LE: 24 mmHg) was elevated, with gonioscopic examination revealing angle closure, consistent with other reported in patients with TMEM98 variants." (PMID 37419942, 2023).
myopia (4 papers, 2020 to 2023). "More common TMEM98 variants have also been associated with myopia in genome-wide association studies." (PMID 37419942, 2023). "Variants close to the 5’ end of TMEM98 are associated with myopia in genome wide association studies, in which the minor alleles are associated with myopia and most likely a larger eye." (PMID 32236127, 2020). "Interestingly, TMEM98, which encodes a single transmembrane protein of unknown function, is also one of the several loci associated with high myopia in genome-wide association study (GWAS)." (PMID 33755662, 2021). "TMEM98, which encodes a widely expressed single transmembrane protein of unknown function, is one of several loci associated with high myopia in GWAS, but a definitive and mechanistic role for TMEM98 in axial length has not been apparent from GWAS." (PMID 32667907, 2020).
hyperopia (3 papers, 2020 to 2025). A refractive error in which rays of light entering the eye parallel to the optic axis are brought to a focus behind the retina, as a result of the eyeball being too short from front to back. "Several genes (e.g., BEST1, CRB1, MFRP, PRSS56 and TMEM98) which have roles in both foetal ocular development and post-natal outer retinal maintenance, can be associated with high hyperopia and short axial length." (PMID 41465105, 2025). "While the physiological role of FRAT proteins is still elusive, TMEM98 has been genetically linked to autosomal dominant nanophthalmos, a developmental disorder resulting in small eyes, hyperopia and an increased risk of angle closure glaucoma." (PMID 31961879, 2020).
hepatocellular carcinoma (2 papers, 2017 to 2023). A malignant tumor that arises from hepatocytes. "TMEM98 was proposed as one of the signature genes for adenocarcinoma and also described as a novel chemoresistance-conferring gene in hepatocellular carcinoma." (PMID 29152140, 2017). "Transmembrane protein 98 (TMEM98), known as a novel gene related to lung cancer, hepatocellular carcinoma, differentiation of T helper 1 cells and normal eye development, has no defined role reported in terms of atherosclerosis (AS)." (PMID 29152140, 2017).
lung carcinoma (2 papers, 2017 to 2018). "In lung cancer, TMEM98 mRNA expression is higher in cancer tissues compared to healthy tissues." (PMID 30574087, 2018). "Furthermore, in two lung cancer cell lines, A549 and H460, the silencing of TMEM98 inhibited cell proliferation and suppressed the invasion and the migration of cancer cells meaning that this protein can have an impact in tumor growth." (PMID 30574087, 2018).
atrial fibrillation (1 paper, 2025). A disorder characterized by an electrocardiographic finding of a supraventricular arrhythmia characterized by the replacement of consistent P waves by rapid oscillations or fibrillatory waves that vary in size, shape and timing and are accompanied by an irregular ventricular response. "A recent study validated a set of five differentially expressed and co-upregulated genes (DEGs) (DGAT1, AMOT, PDE11A, TYMS, and TMEM98) that were elevated in patients with atrial fibrillation, liver disease, and atrial fibrillation associated with liver disease compared to healthy controls." (PMID 40141794, 2025).
gastric cancer (1 paper, 2023). A primary or metastatic malignant neoplasm involving the stomach. "For example, in glioblastoma cells TMEM45A promoting cell proliferation, migration, and invasion and TMEM98 in gastric cancer, among others." (PMID 37936608, 2023). "TMEM98 has also been reported to be involved in increased cell proliferation in gastric cancer." (PMID 37936608, 2023).
head and neck squamous cell carcinoma (1 paper, 2023). A squamous cell carcinoma that arises from any of the following anatomic sites: lip and oral cavity, nasal cavity, paranasal sinuses, pharynx, larynx, and salivary glands. "Recently, TMEM98 was reported to be involved in increased cell proliferation and migration in head and neck squamous cell carcinoma (HNSCC)." (PMID 37936608, 2023).
hyperlipidemia (1 paper, 2017). "In our present study, we strikingly found that significantly high secretion and expression of TMEM98 in hyperlipidemia patients’ serum as well as AS mice's serum and plagues." (PMID 29152140, 2017). "We found the secretion of TMEM98 protein in hyperlipidemia patients was higher than in healthy controls (paired 2-tailed t test, P < 0.05)." (PMID 29152140, 2017). "In our present vivo studies, TMEM98 protein level significantly increased in serum of hyperlipidemia patients and AS mice." (PMID 29152140, 2017).
ovarian carcinoma (1 paper, 2023). A malignant neoplasm originating from the surface ovarian epithelium. "The low expression of TMEM98 in ovarian cancer is correlated with shorter survival time in patients, promoted proliferation, migration, invasion, vasculogenic mimicry, and inhibited apoptosis in SKOV3 and IOSE80 ovarian cancer cell lines." (PMID 37936608, 2023). "In addition, low expression of TMEM98 promoted ovarian cancer development in vivo in female nude mice." (PMID 37936608, 2023). "Recently, it was reported that TMEM98 exerts a tumor-suppressor effect on ovarian cancer." (PMID 37936608, 2023).
cancer (5 papers, 2017 to 2023). A tumor composed of atypical neoplastic, often pleomorphic cells that invade other tissues. "Computer analysis identified the TMEM98 mRNA target protein as the RNA-binding protein nuclear factor 90 (NF90) to which TMEM98 mRNA binds through an 8-nucleotide motif, but the underlying mechanism of this binding remains unclear, but, whether the cancer-promoting effect through TMEM98 mRNA." (PMID 37936608, 2023). "Knowing that tumor progression and chemoresistance can be accompanied with inflammation injuries and the link between TMEM98 and inflammation, this protein is a very interesting target for further investigations on anti-cancer drug resistance." (PMID 30574087, 2018). "In adenocarcinoma, TMEM98's high expression leads to the worst prognosis of adenocarcinoma than other types of cancer." (PMID 29152140, 2017). "So far, we are observed that some TMEM proteins, such as TMEM48, TMEM45B, and TMEM168, are involved in tumor growth, proliferation, migration, and cell invasion through the Wnt/β-catenin pathway, while TMEM170B and TMEM98 act as cancer developmental inhibitors through the same pathway." (PMID 37936608, 2023). "In addition, TMEM98 is a member of single‐pass transmembrane proteins of the endoplasmic reticulum that shows dysregulation in various cancers." (PMID 37937323, 2023). "A bioinformatics analysis showed that the TMEM98 mRNA, in its 3 ́ UTR region has a binding site for Mir-29c-5p, at the same time an bioinformatics analysis showed that low levels of Mir-29c-5p expression were associated with a poor prognosis in patients with this type of cancer." (PMID 37936608, 2023). "It was revealed that several top up‐regulated genes such as KANK1, GALNT14, TMEM98, and PTPN3 and top down‐regulated genes such as PITX2, SNCA, and EPHA7 play key roles in cancer progression and chemotherapy response." (PMID 37937323, 2023). "The repressive effect from Tmem98 implies that mammalian MYRF can be regulated on the membrane in vivo, while the regulators are not necessarily expressed in cultured cancer cells." (PMID 33950834, 2021).
tumor (4 papers, 2017 to 2024). "This study also showed that TMEM98 mRNA expression was higher in tumor tissue of patients who received a transarterial chemoembolization treatment." (PMID 30574087, 2018). "This opens the possibility that TMEM98 acts as a tumor suppressor at the protein level." (PMID 37936608, 2023). "It has been shown that some TMEM proteins are involved in tumor growth, proliferation, migration, and cell invasion through the Wnt/ b-catenin pathway, such as TMEM48, TMEM45B, and TMEM168, whereas TMEM170B and TMEM98 act as tumor development inhibitors through the same pathway." (PMID 38850316, 2024).
TMEM98 also shares sentences with these, for which no sentence is quoted: retinal degeneration (2 papers); adenocarcinoma (1); angle-closure glaucoma (1); atherosclerosis (1); head and neck carcinoma (1); liver disease (1); vasculopathy (1).